RN7SL531P (RNA, 7SL, cytoplasmic 531, pseudogene)
Gene: Miscellaneous RNA gene on chromosome 2 (43,492,032 to 43,492,313, forward strand). Ensembl gene ENSG00000264071.
Homologues: Orthologues: chimpanzee Metazoa_SRP (99% identical), macaque Metazoa_SRP (33% identical). Paralogues in human: Metazoa_SRP (87% identical), Metazoa_SRP (77% identical), Metazoa_SRP (74% identical), Metazoa_SRP (73% identical), RN7SL455P (71% identical), Metazoa_SRP (70% identical), Metazoa_SRP (69% identical), Metazoa_SRP (68% identical), Metazoa_SRP (67% identical), Metazoa_SRP (66% identical), Metazoa_SRP (64% identical), Metazoa_SRP (62% identical), and 707 more.